IL10 (interleukin 10)
Diseases named in the same sentence as IL10 in open-access papers (continued):
Sharing a sentence is not in itself a finding about the gene and the disease.
tumor (continued). "In the tumor microenvironment (TME), TREM2+ macrophages display a transcriptional program enriched for immunosuppressive mediators such as IL-10, TGF-β, and arginase-1 (ARG1), and show reduced expression of antigen-presentation molecules (e.g., MHC-II)." (PMID 40821795, 2025). "M1-polarized macrophages possess anti-tumor functions, whereas M2-polarized macrophages promote tumor angiogenesis, EMT, and immune suppression by secreting anti-inflammatory factors and pro-angiogenic factors such as TGF-β, IL-10, and VEGF-C." (PMID 41438986, 2025). "Tumor‐derived GM‐CSF, IL‐6 and VEGF‐A attract MDSCs, which inhibit T‐cell responses via TGF‐β, IL‐10, arginase (ARG)‐1 and reactive oxygen species." (PMID 41143064, 2025). "Within the tumor TME, expression of immunosuppressive cytokines such as IL-6, IL-8, IL-10 and TGF-ß contribute to MHC downregulation." (PMID 40676060, 2025). "Acting synergistically, IL-10 and TGF-β establish an immunosuppressive microenvironment that inhibits anti-tumor immune responses." (PMID 41333481, 2025). "For instance, M2 macrophages that secrete IL-10 can downregulate IL-12 expression in dendritic cells, subsequently impairing the activation of CD8+ T cells, and thereby allowing tumor cells to evade immune detection." (PMID 40570022, 2025). "Concurrently, CAFs suppress the anti-tumor activities of immune cells through the secretion of immunosuppressive factors such as TGF-β, IL-10, and PGE2." (PMID 40104498, 2025). "In an in vivo breast cancer model, Tα‐1 in conjunction with Epirubicin treatment markedly slowed down the growth of the tumor by decreasing IL10 produced by macrophages and increasing the quantity and quality of CD4+ and CD8+ T cells that infiltrate the tumor." (PMID 39748782, 2025). "For instance, tumor cells can release inhibitory substances such as transforming growth factor beta (TGF-β) and interleukin-10 (IL-10), which hinder the activity and proliferation of NK cells." (PMID 40308592, 2025). "N2 TANs produce immunosuppressive cytokines such as IL-10 and transforming growth factor-beta (TGF-β), which inhibit the activity of cytotoxic T lymphocytes (CTLs) and natural killer (NK) cells, allowing tumor cells to evade immune surveillance." (PMID 41180630, 2025). "M2 macrophages secrete immunosuppressive factors (such as IL-10 and TGF-β), promoting tumor immune evasion and angiogenesis, thereby providing a favorable environment for tumor cell growth and metastasis." (PMID 40557321, 2025). "Tregs achieve this through several mechanisms, including the secretion of immunosuppressive cytokines like IL-10 and TGF-β, which dampen immune responses and promote an anti-inflammatory environment favorable to tumor survival." (PMID 40453074, 2025). "TAMs promote tumor progression through stimulation of angiogenesis, secretion of IL-10, TGFβ, and VEGF-A, and driving of tumor cell migration, invasion, and metastasis." (PMID 40646332, 2025). "M0 macrophages also release immunosuppressive cytokines like IL-10 and TGF-β, which can diminish T cell activity and impair the immune system's ability to target tumor cells, thereby facilitating tumor evasion." (PMID 39895793, 2025). "Consistent with previous reports on other tumor-targeting IgE antibodies, 16 20 anti-HER2 IgE cross-linking, also stimulated upregulation of CCL2, and of the anti-inflammatory mediator IL-10." (PMID 40074330, 2025). "Central to this “barrier effect” are cancer-associated fibroblasts (CAFs)—mesenchymal cells that, in response to cytokines such as IL-10 and TGF-β secreted by tumor cells, produce abundant extracellular matrix proteins." (PMID 40647513, 2025). "Canonical NF-κB signaling, triggered by pathways such as TLR2/4-MyD88 and TNFR/TNFR2, enhances MDSC immunosuppression by increasing IL-10 and TGF-β production, thereby dampening T-cell responses and fostering tumor progression." (PMID 40562870, 2025).
tumor (continued). "For example, IL-10 and TGF-β encourage Treg differentiation, which in turn suppresses anti-tumor immune responses." (PMID 39861138, 2025). "Tumor-produced PGE2 (via COX-1/2) and IL-6 can likewise inhibit DCs differentiation through STAT3 signaling, skewing DCs to produce more IL-10 but less IL-12, thereby promoting regulatory or TH2 responses over TH1 cytotoxic immunity." (PMID 41488634, 2025). "Cytokines, such as CCL-2, IL-6, IL-8, IL-10, IL-13, and TNF-α, exhibit tumor-specific secretion profiles." (PMID 40777043, 2025). "They drive NKs exhaustion and facilitate tumor immune escape by depleting activation factors like IL-2, releasing immunosuppressive molecules such as TGF-β and IL-10, and activating inhibitory receptors on NK cells, including PD-1 and TIGIT." (PMID 40008144, 2025). "This suppressed PI3Kγ signaling, reducing the expression of M2 markers (CD206 and IL-10) and increasing the expression of M1 markers (CD86 and TNF-α), which inhibited tumor growth by reprogramming TAMs in 4T1 and MC38 mouse models." (PMID 40850976, 2025). "FoxP3+ Tregs establish a robust immunosuppressive network by overexpressing checkpoint molecules (CTLA-4, PD-1, LAG-3) and secreting inhibitory cytokines (IL-10, TGF-β, IL-35), thereby creating an immune-privileged niche for tumor survival." (PMID 40563359, 2025). "Myeloid-derived suppressor cells (MDSCs), expanded by tumor-derived signals, produce immunosuppressive cytokines (e.g., TGF-β, IL-10) and enzymes (e.g., ROS, arginase, NO) that inhibit cytotoxic T cells, dendritic cells, and NK cells." (PMID 41311372, 2025). "The subsequent signaling cascade eventually leads to the activation of NF-κB and an increase in pro-inflammatory cytokine levels (IL-10 and INF) in the tumor, thereby promoting carcinogenesis." (PMID 40927726, 2025). "TAMs secrete immunosuppressive cytokines such as IL-10 and TGF-β, which inhibit the function of effector T cells and NK cells, thereby dampening anti-tumor immune responses." (PMID 41280929, 2025). "In adoptive cell therapy, using DCs treated with IL-2, PBMCs, KRASG12D1−23 peptide, or tumor lysates resulted in the increase of CD8+ T cells and decrease of TH1 cells, TGF-β and IL-10." (PMID 40611261, 2025). "Propionibacterium acnes, frequently enriched in GC tissues, especially in H. pylori–negative cases, promotes M2 macrophage polarization via TLR4/PI3K/Akt signaling, resulting in IL-10 and CCR-2 secretion that fosters immunosuppression and tumor progression." (PMID 41189901, 2025). "pDCs within the tumor microenvironment inhibit the anti-tumor functions of CD8+ T cells and NK cells by releasing immunosuppressive cytokines (IL-10 and TGF-β) and promoting the proliferation of Tregs." (PMID 41409300, 2025). "Hypoxia directly impairs the function of tumor-infiltrating lymphocytes (TILs) and upregulates immunosuppressive signals such as PD-L1, TGF-β, IL-6, and IL-10 within the tumor microenvironment." (PMID 40260303, 2025). "TAMs can inhibit antitumor immune responses through the secretion of immune-suppressive factors such as IL-10 and TGF-β, thus providing an opportunity for tumor cells to survive and recur after treatment." (PMID 40850976, 2025). "These cells release anti-inflammatory cytokines, including interleukin-10 (IL-10), transforming growth factor-beta (TGF-β), and other protumor mediators that inhibit effector immune responses and foster a tolerogenic and tumor-supportive milieu." (PMID 40567374, 2025). "Moreover, IL-10 secreted by Tregs may potentiate the transformation of macrophages to M2-polarized macrophages along with inhibition of the DCs maturation, which, in turn, prevents DC-mediated antigen presentation and hinders tumor reduction." (PMID 41007774, 2025). "Tregs maintain immune homeostasis by producing inhibitory cytokines (IL-10, IL-35, TGF-β), suppressing excessive immune activity, though their hyperactivity can impair anti-tumor immunity." (PMID 40443668, 2025).
tumor (continued). "Cytokines and chemokines secreted by tumor cells, such as IL10, CCL2, and CSF1, are key drivers of TAM plasticity within the pro-tumor microenvironment." (PMID 40730813, 2025). "M2-like TAMs, in particular, are associated with a pro-tumoral environment, marked by the secretion of immunosuppressive cytokines like IL-10 and TGF-β, which not only enhance tumor growth but also hinder the immune response." (PMID 40079009, 2025). "Tumor-infiltrating Bregs with a CD19+CD38+CD1d+IgM+CD147+ phenotype have been identified and express key regulatory molecules including IL-10, CD25, and IDO, contributing to suppression of antitumor immune responses." (PMID 40231472, 2025). "In contrast to peripheral CD56dimCD16+ cells, which maintain cytotoxic function, tumour-infiltrating CD56brightCD16− NK cells secrete VEGF and IL-10 to promote pathogenesis and immunosuppression." (PMID 41429765, 2025). "On one hand, this pathway upregulates the expression of cytokines with immunosuppressive functions, such as interleukin 10 (IL-10), and transforming growth factor β (TGF-β), in the tumor microenvironment." (PMID 41373839, 2025). "Inhibits tumor growth, induces tumor cell apoptosis, increases M1-type macrophages in tumor tissue, elevates TNF-α and IL-6, and reduces IL-10." (PMID 40766304, 2025). "C5aR1 inhibitors reduce the release of immunosuppressive factors, such as IL-10 and TGF-β, in the tumor microenvironment." (PMID 41373839, 2025). "Cytokines such as TGF-β, IL-6, IL-10, and TNF-α play critical roles in tumor progression and metastasis." (PMID 40443678, 2025). "M2c macrophages mediate potent immunosuppression via IL-10 and TGF-β secretion, supporting tumor survival." (PMID 40948759, 2025). "In fact, PGE2 impairs DC migration in tumor‐draining lymph node and TME in models of prostate cancer, and PGE2‐primed DC produce higher levels of the immunosuppressive cytokine IL‐10, which in turn downregulates their APC activity." (PMID 39973474, 2025). "These cytokines represent complementary aspects of the tumor microenvironment: pro-inflammatory and tumor-promoting signaling (IL-6, IL-1β, TNF-α), anti-inflammatory modulation (IL-10), and Th17-driven immune activity (IL-17)." (PMID 41267807, 2025). "We found that knockdown of AXL significantly reduced the expression of CCL-2, CSF-1, IL-10, and TGF-β cytokines in ccRCC tumor cells." (PMID 41029360, 2025). "In parallel, IL-10 reduces the production of pro-inflammatory cytokines such as IL-1β and TNF-α in neutrophils, further stabilizing the N2 phenotype and dampening anti-tumor immune responses." (PMID 40281554, 2025). "M2-polarized TAMs secrete IL-10, VEGF and other factors promote angiogenesis and immunosuppression, thereby dampening anti-tumor activity of T cells." (PMID 40787471, 2025). "Within the tumor microenvironment (TME) and in chronic inflammatory settings, elevated TGF-β and IL-10 suppress effector T cell activation while expanding Tregs, fostering an immunosuppressive milieu." (PMID 40155378, 2025). "Biochemical analysis of mouse blood samples showed that the levels of tumor marker CEA and inflammatory factor TNF-α were increased in the microbial treatment group (p < 0.01), while IL-10 (an anti-inflammatory factor) was decreased (p < 0.01)." (PMID 41562055, 2025). "By secreting immunosuppressive cytokines such as IL-10, TGF-β, and PGE2, N2 neutrophils inhibit the activation of cytotoxic T cells and NK cells, which are essential for eliminating metastatic tumor cells." (PMID 40486595, 2025). "Conversely, M2 macrophages promote immunosuppression via IL-10, TGF-β, and arginase-1 (Arg-1) expression, facilitating tissue repair, angiogenesis, and tumor progression." (PMID 40563359, 2025). "In protumorigenic immune microenvironments, Th2 cells exhibit elevated levels of cytokines such as IL-10 and TGF-β and contribute to tumor progression." (PMID 39744942, 2025).
tumor (continued). "Hypoxia-induced expression of VEGFA potentiates the ability of interleukin-10 (IL-10) and prostaglandin-E2 (PGE2) to drive expression of Fas ligand (FasL) on tumor ECs to selectively induce apoptosis of cytotoxic T cells but leave Treg cells unscathed." (PMID 39567756, 2025). "Future research should focus on discovering novel cytokine and growth factor biomarkers, particularly underexplored molecules like IL-10, TGF-β, and CXCL12, which influence immune evasion and tumor progression." (PMID 40881677, 2025). "GSEA using Reactome terms identified increased interleukin activity of tumor-infiltrating DCs with IL4, IL13, and IL10 predicted to elicit the greatest impact on infiltrating DCs." (PMID 39932553, 2025). "The immunosuppressive effects of IL-10 and PGE2, which suppress T-cell activity, further promote tumor progression." (PMID 41201629, 2025). "We also examined the presence of tumor-specific CD4+ and CD8+ T lymphocytes that produce IFN-γ and IL-10 in the spleens and lymph nodes of OpdA-treated animals." (PMID 41019059, 2025). "Elevated levels of IL-2 and IFN-γ, and decreased IL-10 were observed in OSCC patients, correlating with tumor differentiation and stage." (PMID 40958269, 2025). "In contrast, IL-10 and TGF-β promote M2 polarization via STAT3 and Smad signaling, increasing arginase-1 and PD-L1 expression, suppressing anti-tumor immunity." (PMID 41244711, 2025). "Several cytokines are known to be involved in tumor development and immune modulation, including tumor necrosis factor (TNF)-α, IL-6, IL-10, IL-12, IL-17, transforming growth factor (TGF)-β, and macrophage migration inhibitory factor (MIF)." (PMID 41051525, 2025). "In groups with elevated IL-10 and TGF-β1 expression, immune checkpoint genes exhibited consistent upregulation, with significantly higher expression in tumor samples compared to normal samples." (PMID 41438510, 2025). "The secretion of TGF-β, IL-10, PGE2, VEGF, and metalloproteinases alters the tumor microenvironment to promote immune evasion and facilitates non-immunological tumor progression." (PMID 41465319, 2025). "PD-L1 is upregulated on tumor cells in response to INF-γ, leading to an increase in IL-10 secretion and activated T cell death, making tumor cells more resistant to cell death." (PMID 40227644, 2025). "Meanwhile, we performed flow cytometry to quantify cytokine production in tumor-infiltrating γδ T cells, including IL-17, TNF-α, IFN-γ, IL-4, IL-10, and TGF-β." (PMID 41055972, 2025). "It is demonstrated that the tumor microenvironment (TME) is dominated by immunosuppressive cytokines, including interleukin-10 (IL-10), transforming growth factorβ (TGFβ), and IL-35." (PMID 40281554, 2025). "The M2‐polarized phenotype of TAMs is an important feature of the ESCC microenvironment, and M2‐type macrophages promote tumor immune escape and angiogenesis by secreting factors such as VEGFA and IL‐10." (PMID 40529613, 2025). "An increased production of anti-inflammatory IL-10 and IL-17 by M2-like macrophages has been found to induce the expression of ECM degradation enzymes and angiogenic markers, thus supporting tumor angiogenesis and migration." (PMID 40710006, 2025). "In colorectal cancer, tumor cells release IL-4 to promote the expression of CD155 on TAMs,108 thus facilitating their M2 polarization and increasing the expression of IL-10 and TGF-β, thereby supporting tumor progression." (PMID 40055311, 2025). "Tumor-derived signals promote macrophage polarization toward a pro-tumoral M2-like phenotype, supported by IL-4, IL-13, IL-10, TGF-β, hypoxia, immune complexes and tumor metabolites." (PMID 41230456, 2025). "The combined effects of IL-10, TNF-α, and IFN-γ further induce B7-H4 on tumor cells, thereby promoting T-cell apoptosis and impeding cytotoxic lymphocyte-mediated tumor eradication." (PMID 41058699, 2025).
tumor (continued). "In most tumors, M2 macrophages express ARG1 and CD206 while secreting IL-10 and TGF-β, thereby promoting angiogenesis, matrix remodeling, and immunosuppression to maintain tumor cell growth." (PMID 41035634, 2025). "Conversely, M2-like TAMs play crucial roles in promoting tumor metastasis, invasion and drug resistance and generate immunosuppressive factors, including TGF-β and IL-10." (PMID 40943546, 2025). "Macrophages facilitate tumor growth, invasion, and immunosuppression via pathways involving TNF, Fas ligand, and IL-10." (PMID 40636453, 2025). "These cells promote immune suppression and angiogenesis by secreting IL-10 and TGF-β, which inhibit T cell and NK cell activity, while also supporting brain development and tumor invasion." (PMID 40443668, 2025). "Elevated cytokine levels, including IL1α, TNFα, IL6, IL10, IL17, and IL12, represent the rejuvenation of tumor immunity in response to combination ICI." (PMID 40313772, 2025). "These M2-polarized TAMs secrete anti-inflammatory and pro-tumoral factors (e.g., interleukin (IL)-10, transforming growth factor (TGF-β), vascular endothelial growth factor) and inhibit effective anti-tumor immunity, correlating with poor patient outcomes." (PMID 41465516, 2025). "Neutrophils can also secrete immunosuppressive cytokines such as interleukin-10 (IL-10) and transforming growth factor-beta (TGF-β), which inhibit T-cell proliferation and cytokine production, further dampening anti-tumor immune responses." (PMID 41180630, 2025). "M2 macrophages secrete IL-10 and TGF-β, inhibiting effector T cells and NK cells, while tumor-derived signals drive their polarization." (PMID 41181115, 2025). "These EVs also carry immunosuppressive molecules, including PD-L1, TGF-β, and IL-10, which inhibit T cell activation or promote components of immune suppressive TME, such as Tregs and MDSCs, further dampening anti-tumor immunity." (PMID 40574844, 2025). "Recruitment of Tregs in TME is also widely noticed as a method for tumor immune escape, Capable of autocrine immunosuppressive cytokines, Tregs secrete tumor growth factor-β (TGF-β), IL-10, and IL-35 to inhibit the proliferation and activation of T cells." (PMID 40709184, 2025). "TAM can then secrete IL-10, GF-β, EGF, WNT, etc. to influence the signal transduction pathway in tumor cells, leading to the proliferation and metastasis of tumor cells." (PMID 38602556, 2024). "Among the mechanisms that regulate PD-L1 expression, the production of cytokines, such as IL-1a, IL-27, IL-10, and IL-32g, in the tumor microenvironment (TME) can upregulate the expression of PD-L1 on monocytes and tumor cells." (PMID 38543183, 2024). "M2-TAM can secrete IL-10, arginase 1 (Arg-1), programmed death ligand 1 (PD-L1), TGF-β and VEGF, which are conducive to tumor growth." (PMID 38244580, 2024). "In tumorigenic conditions, M2c macrophages act similarly to M2a macrophages as they both release anti-inflammatory cytokines for instance IL10 and TGF-β, as well as induce tumor invasion and metastasis through expression of VEGF and MMPs." (PMID 38935134, 2024). "HRS cells overexpress key immunosuppressive molecules like IL-10, TGF-beta, and galectin-1 to create an immune-suppressive microenvironment and prevent effective anti-tumor immune responses." (PMID 38539461, 2024). "During tumor immunity, Tregs suppress excessive immune responses and promote immune escape of tumor cells by expressing inhibitory factors such as CTLA4, IL-10, and TGF-β." (PMID 38745661, 2024). "This reduction can be attributed to the tumor releasing immunosuppressive factors, such as TGF-β, IL-10, during its growth." (PMID 38263363, 2024). "TAMs promote angiogenesis by secreting VEGF, induce Treg differentiation through IL-10 and TGF-β secretion, and are recruited to tumor sites by tumor-derived CSF-1." (PMID 39770505, 2024).